IL1B (interleukin 1 beta)
Diseases named in the same sentence as IL1B in open-access papers (continued):
Sharing a sentence is not in itself a finding about the gene and the disease.
tumor (continued). "Here, we show that the secretion of TNF-α and IL-1β by tumor-bearing dogs is gradually decreased after administration of pardaxin, implying that pardaxin may induce tumor cell apoptosis at dog tumor sites." (PMID 25544775, 2015). "Although this study focused on the role of IRAK1-driven cytokine network in a cancer cell autonomous manner, IL-1β-mediated IRAK1 activation via tumour-infiltrating immune cell–tumour cell interaction may further enhance oncogenic activity of IRAK1 in vivo." (PMID 26503059, 2015). "M2 macrophages promote tumor progression by enhancing angiogenesis and inhibiting an immune response against tumors, whereas M1 macrophages promote a proinflammatory microenvironment by releasing IL-1β, IL-6, IL-12, and tumor necrosis factor alpha (TNF-α)." (PMID 26131447, 2015). "The role of inflammasomes in carcinogenesis is contrasting; they may inhibit tumor promotion by activating caspase-1 and cell killing, or may promote tumor growth by upregulating secretion of pro-inflammatory molecules like, IL-1β, IL-18, FGF2 and HMGB1." (PMID 26689911, 2015). "Among these, most genes modulated by IL-1β appeared to be related to cell differentiation (283 genes), tumor cell proliferation (178 genes), apoptosis (315 genes), and the development of cardiovascular system and blood vessels (168 and 135 genes, respectively)." (PMID 26114549, 2015). "Furthermore, we found that metformin alleviates tumor inflammation by reducing the expression of inflammatory cytokines including IL-1β as well as infiltration and M2 polarization of tumor-associated macrophages (TAMs) in vitro and in vivo." (PMID 26641266, 2015). "Local administration of recombinant IL-1β and IL-12 fully restored anti-tumor T cell responses in P2RX7−/−, NLRP3−/− and Caspase-1−/− mice, suggesting that the use of biologics may potentially benefit patients that have defects in these pathways." (PMID 26486085, 2015). "In addition, IL-16 can activate the secretion of tumor-associated inflammatory cytokines, such as TNF-α, IL-1β, IL-6, and IL-15, all of which are major factors involved in tumorigenesis." (PMID 25954818, 2015). "Third, by RT-qPCR analyses, TANs showed downregulation of anti-tumor genes (e.g., il4, il6, il8, il10, il12, and tnfa) and upregulation of pro-tumor genes such as il1b, which also promotes early cancer angiogenesis, indicating a potential role of TANs in pro-angiogenesis in HCC initiation." (PMID 25828472, 2015). "The presence of IL-1β in the tumor microenvironment promotes the development of aggressive RCC by inducing the expression of matrix metalloproteinase (MMP) 1, MMP3, MMP10 and MT1-MMP via activation of the transcription factor CCAAT enhancer binding protein β (CEBPβ)." (PMID 26486078, 2015). "Moreover, cancer cells, tumor-derived fibroblasts, and antigen-presenting cells secrete several key cytokines for Th17 differentiation such as IL-1β, IL-6, IL-23, and TGF-β." (PMID 26583099, 2015). "In OC, IL-1β also promotes invasiveness and tumor angiogenesis and induces immune suppression." (PMID 26357657, 2015). "The effect of circulating IL-1β in serum on migration of cancer cells to lungs has been supported by another report, which shows that injection of recombinant IL-1β into blood can promote experimental lung metastasis of tumor." (PMID 25706411, 2015). "Previous studies have showed that EP2 could promote cell growth and invasion through upregulation of the tumor-promoting inflammatory cytokines, such as IL-1β and IL-6." (PMID 25781635, 2015). "Microenvironmental IL-1β is believed to play an important role in tumor invasion." (PMID 25955408, 2015). "Correspondingly, we found Nampt/PBEF/visfatin to positively correlate with the expression of inflammatory mediators with IL1β being an independent predictor for its tumor and normal colorectal tissue expression and IL1β and IL8 for its expression in whole blood." (PMID 26075243, 2015).
tumor (continued). "Therefore, our data suggest that tumor-derived IL-1β is a negative regulator of hMSC niche formation." (PMID 26204886, 2015). "We have presently analyzed inflammation-related factors in whole tumor samples, having found that the pro-inflammatory cytokine IL-1β and the anti-inflammatory cytokine IL13 expression was altered (higher and lower, respectively) in cachectic cancer patients, as compared to WSC." (PMID 26732354, 2015). "Others have shown that overexpression of IL-1β in the mouse stomach results in tumor induction." (PMID 25528766, 2015). "Additionally, numerous soluble mediators, including TNF-α, TGF-α, TGF-β, IL-1β, IL-1α, IL-6, IL-8, VEGF, and others have been implicated in PC carcinogenesis, tumor progression, and treatment resistance." (PMID 26498838, 2015). "Furthermore, studies have shown that blocking IL-1β signaling reduces the anti-tumor effect of anthracyclines and oxaliplatin." (PMID 24474192, 2014). "Conversely, in the HER2-negative cohort, which is different from the HER2-positive arm for the biology of the tumor, the NC treatment, and also for the immune profile at diagnosis, we observed changes in IL-1α, IL-1β, IL-2, IL-6, and GM-CSF levels already at week 12 of ED treatment." (PMID 25512030, 2014). "Therefore, Curcumin should be tested in an appropriate tumor model and compared with agents specifically targeting IL-1β signaling, such as canakinumab." (PMID 24901233, 2014). "Moreover, these processes are further potentiated by inflammatory cytokines found in the tumor microenvironment, such as TNFα and IL-1β." (PMID 24598028, 2014). "Finally, this review demonstrated the important role of the IL-1 family molecules, especially IL-1β, in the tumor microenvironment." (PMID 24734023, 2014). "Since IL-1β is important for the anti-tumor immune response, it has been speculated that genetic variations that modify the expression of IL-1β may influence the risk of MM." (PMID 25202401, 2014). "IL-1β released by stromal cells together with other tumor-derived factors, including granulocyte macrophage colony-stimulating factor (GM-CSF), cyclooxygenase 2 (COX-2), IL-6, and VEGF, induce the accumulation and expansion of MDSCs by triggering Janus kinase (JAK)/STAT3 pathways." (PMID 25136593, 2014). "Interestingly, ALT-803 alone resulted in similar tumor reduction and production of urinary IL-1α, IL-1β and RANTES, which also led to the activation and proliferation of CD8a+ T-cells." (PMID 24896845, 2014). "Interleukin-1 beta (IL-1β) is an important mediator of tumor angiogenesis." (PMID 24787299, 2014). "Although the NAIP5/NLRC4 inflammasome-mediated IL-1β secretion in response to the injection of flagellin-modified tumor cells, it is unclear whether the involvement of this cytokine was necessary for the success of this immunotherapy." (PMID 25071770, 2014). "Upregulation of IL-1β and IL-6 could potentially serve as autocrine positive feedback loop for TP in cancer cells and drive paracrine induction of the enzyme in tumor microenvironment." (PMID 24819505, 2014). "Inflammatory cytokines such as interleukin-6 (IL-6), tumor necrosis factor alpha (TNF-α), and interleukin-1 beta (IL-1β) produced by the tumor or adipose tissue may also contribute to adipose depletion." (PMID 25415607, 2014). "Nevertheless, the TP-overexpressing tumor cells exhibited enhanced expression of IL-1β and IL-6." (PMID 24819505, 2014). "TNF-α and Il-1β are significant regulators of host defense against tumor cells." (PMID 24348858, 2014). "IL-1β aids in tumor invasiveness and adhesion required during metastasis to new sites." (PMID 24782866, 2014). "Recent studies reported that CAFs associated to incipient neoplasia are able to exhibit a pro-inflammatory signature, characterized by an over-expression of SDF-1, IL-6, and IL-1β that contribute to the recruitment of pro-angiogenic macrophages sustaining tumor growth." (PMID 25072019, 2014).
tumor (continued). "However, E-selectin expression at the surface of endothelial cells is induced by tumor-derived IL-1α and monocyte-induced IL-1β in inflammatory metastatic sites." (PMID 25255877, 2014). "However, only 50% of the tumor samples had increased IL-1β and IL-23, which are also important in Th17 development and maintenance." (PMID 23365642, 2013). "However, AKT depletion does cause an increase in IL1B, which inhibits the function of KGF by reducing the expression of its receptor, FGFR2b, in tumour cells." (PMID 23867201, 2013). "They found that tumor cells induce the release of interleukin (IL)-1β by THP-1 macrophages." (PMID 24202444, 2013). "This may represent a unique scenario in which a low tumor burden, possibly accompanied by relative low levels of IL-1β in the microenvironment could activate local immunity." (PMID 23847618, 2013). "We identified tumor-derived IL1β as one potential mediator of the observed phenotype." (PMID 24405819, 2013). "Furthermore, TNF-α and IL-1β supported tumor immune escape in vitro, by inducing the expression of TNF-related Apoptosis-inducing Ligand (TRAIL) on the surface of liver cancer cells, which in turn promoted apoptosis of activated T cells." (PMID 23533994, 2013). "MSCs responded mainly to tumor cell lines which express high levels of IL1β." (PMID 24405819, 2013). "We have shown that IL-1β inhibition stably reduces tumor growth, by limiting inflammation and by inducing the maturation of MDSCs into M1 macrophages, which do not promote tumor invasiveness and can be cytotoxic/cytostatic for tumor cells and can also serve as APCs that induce anti-tumor immunity." (PMID 23847618, 2013). "In addition, bioinformatics and pathway analysis of gene expression data from tumor cell lines combined with experimental validation revealed tumor-derived IL1β as one mediator of the pro-inflammatory phenotype observed in MSCs exposed to tumor CM." (PMID 24405819, 2013). "IL-1β has been found overexpressed in NPC tumor samples, an important cytokine for PMN recruiting." (PMID 23638154, 2013). "Enhanced expression of IL1B in the tumour-associated stoma compared to the stroma from matched non-tumour tissue showed a more favourable outcome than those with reduced expression of IL1B in the tumour associated stroma." (PMID 23867201, 2013). "IL-1β thus provides the inflammatory microenvironment for angiogenesis and tumor progression." (PMID 23847618, 2013). "The expression of IL-1β, at least in part, reduced cisplatin-induced tumor cell death." (PMID 23383347, 2013). "Expression of IL-1β by tumor cells also contributes to tumor growth and angiogenesis." (PMID 24273542, 2013). "The production of pro-inflammatory cytokines, IL-1β, IL-6, and TNFα, all of which facilitate tumor growth, in the tumor microenvironment might be due to STAT3 hyperactivation in both the tumor and immune cells." (PMID 23730621, 2013). "Thus, insufficient characterization of IL-1 at tumor sites has led to some inconsistencies concerning the impact of the concerted action of IL-1α and IL-1β on the malignant process." (PMID 23847618, 2013). "The IL1 isoforms, IL1A and IL1B, have previously been described as both anti-invasive and pro-invasive, suggesting no clear indication of their role in cancer progression; however, our findings report a new protective function for IL1B in tumour invasion." (PMID 23867201, 2013). "Similarly, when putting side by side the SiHaparental and SiHaCDV groups at the moment that they have an equivalent tumor size (week 3 and week 5, respectively), IL-1β was detected in higher amounts in the SiHaparental cohort." (PMID 24325392, 2013). "However, in different tumor systems, redundant or unique patterns of IL-1α and IL-1β expression and function have been observed." (PMID 23847618, 2013). "The increased tumor burden correlates with attenuated levels of IL-1β and IL-18 at the tumor site." (PMID 23847622, 2013).
tumor (continued). "Similar to IL8, IL1β also promotes tumor progression by controlling tumor growth and invasion." (PMID 23762239, 2013). "To clarify whether M.hy promoted tumor development via inflammasome activation, we analyzed monocytes for IL-1β and IL-18 production upon M.hy challenge." (PMID 24223129, 2013). "In conclusion, better understanding the integrative role that IL-1α and IL-1β play in animal experimental models and in cancer patients, together with “IL-1 mapping” at tumor sites should pave the way for safe and efficient application of anti-IL-1 therapies at the bedside for cancer patients." (PMID 23847618, 2013). "In mice, tumour-derived IL-1β inhibits tumour growth and enhances survival through host responses." (PMID 23065753, 2012). "Thus, our findings strongly suggest that tumour-derived IL-1β can contribute to local tumour control and better survival." (PMID 23065753, 2012). "Our results indicate that IL-1β is sufficient to induce tumor cell invasion of RCC cells." (PMID 23342250, 2012). "In addition, low levels of IL-1β and IL-12 was detected after H. pylori pretreatment with one of the mucin samples (patient 1 insoluble tumor mucins, high density, at 125 μg/mL)." (PMID 22563496, 2012). "This process is partly dependent on glioma tumor derived cytokines IL-1β and TNF-α, which could plausibly trigger expression and activity of B1R impacting on the brain tumor microcirculatory system." (PMID 22629405, 2012). "Since the inhibitory effect of IL-1β on tumour growth was dependent on IL-1β receptor-mediated signalling of the host immune system, we further investigated the composition of tumour-infiltrated leukocyte subsets from tumours by flow cytometry." (PMID 23065753, 2012). "Middle panel, tumour growth was inhibited by tumour-derived IL-1β in a dose-dependent manner." (PMID 23065753, 2012). "Consistent with this, our data show that IL-1β-induced RCC tumor invasion was dependent on CEBPβ." (PMID 23342250, 2012). "The results suggest that LMP1 can induce pro-IL-1β expression in NPC tumours." (PMID 23065753, 2012). "In one recent study, it was shown that IL-1ra released from PLGA microspheres could inhibit the stimulatory effects of IL-1β on tumor cell progression for at least 7 days." (PMID 22863285, 2012). "Treatment of the RCC cells with IL-1β resulted in induction of tumor cell invasion by 24 h." (PMID 23342250, 2012). "Consistent with their findings, our data show that the inflammasomes in malignant cells are responsive to PAMPs, DAMPs and therapeutic treatment, and the interaction of tumour-derived IL-1β (over 64.2 pg/ml) and its receptors on the host cells can inhibit tumour growth and recurrence." (PMID 23065753, 2012). "Furthermore IL-1β promotes the production of angiogenic proteins from host stromal or infiltrating cells in tumor microenvironment enhancing tumor growth and metastasis." (PMID 23300633, 2012). "We speculate that IL-1β may promote tumor growth by increasing the self-renewal capability of colon CSCs." (PMID 23174018, 2012). "Therefore, we theorize that in the Hr mutant epidermis, increased COX-2 levels in conjunction with TNFα and IL-1β create an pro-inflammatory environment that promotes tumor growth." (PMID 22761871, 2012). "However, the effect of tumour-derived IL-1β on neutrophil infiltration was completely abolished in Il1r1−/− mice." (PMID 23065753, 2012). "Taken together, our findings support the hypothesis that TANs are recruited by tumour-produced cytokines, e.g. IL-1β, and exert a host-mediated cytotoxic effect against the tumour." (PMID 23065753, 2012). "Intraperitoneal recombinant IL-1β administration led to a dose dependent replacement of peritoneal ascitic tumour with solid tumours attached to the peritoneum, and high doses had an anti-tumor effect." (PMID 22296757, 2012). "We hypothesized that IL-1β in the tumor microenvironment promotes the development of aggressive RCC tumors by directing affecting tumor epithelial cells." (PMID 23342250, 2012).
tumor (continued). "In addition, high levels of tumour-derived IL-1β can recruit a large number of TANs, which significantly inhibit tumour growth in mice." (PMID 23065753, 2012). "Importantly, we demonstrate that therapeutic treatment activates the inflammasome in NPC cells and can enhance IL-1β production (from ∼174 to ∼492 pg/ml) in the presence of tumour microenvironmental factors." (PMID 23065753, 2012). "CEBPβ knockdown significantly decreased IL-1β-induced tumor cell invasion." (PMID 23342250, 2012). "Thus, overexpression of AIM2, RIG-I and NLRP3 inflammasomes and IL-1β in tumour cells likely contributes to local tumour control." (PMID 23065753, 2012). "On the other hand, IL-1β can promote tumor angiogenesis and metastasis." (PMID 22778760, 2012). "Extracellular ATP can also function through P2RX7 purinergic receptors to initiate NLRP3 inflammasome activation and subsequent IL-1β production that were all shown to be required for the induction of tumor antigen-specific CD8+ T cells following challenge with dying tumor cells." (PMID 23087904, 2012). "Another potential mechanism by which the quality of priming of Mam-A2.4 specific CD8 T cells may be induced during the treatment of tumor derived DC with irradiation could be via the induction of IL-1β." (PMID 22911764, 2012). "Expression of IL-1β was detected in the different tumor subtypes in tumor cells." (PMID 23270518, 2012). "Preliminary experiments revealed that tumor F98 gliomas implanted in the brains of rats have high levels of IL-1β immunoreactivity, providing support to this hypothesis." (PMID 22629405, 2012). "Consequently, in OC, IL-1β generally promotes invasiveness, tumor angiogenesis and induces immune suppression while IL-1α reduces tumorigenicity by inducing antitumor immunity." (PMID 21765834, 2011). "Such advantages could be given to the tumor cells by the ability of TNFα to promote EMT, and by similar (although to a lower extent) or other tumor-promoting activities of IL-1β (e.g. joint activities with other pro-malignancy elements)." (PMID 21486440, 2011). "Significant associations were found between CCL2 & CCL5 and TNFα & IL-1β in the tumor cells in DCIS and IDC-no-relapse patients." (PMID 21486440, 2011). "In addition to the tumor-promoting activities of TNFα and IL-1β that have already been described, it is possible that these two cytokines also have functional interactions with CCL2 and CCL5, by that promoting disease course." (PMID 21486440, 2011). "Furthermore, recent findings obtained in our studies suggest that TNFα and IL-1β exert tumor-promoting activities that are connected to the ability of CCL2 and CCL5 to function as cancer-supporting factors." (PMID 21486440, 2011). "In the coculture model, IFNγ increased expression of IL-1β, which might favor the development of a pro-inflammatory microenvironment in the tumor." (PMID 21310022, 2011). "The explanation could be given, at least partly, by consideration of the extent to which receptors for TNFα and IL-1β are expressed by the tumor cells, and of which type." (PMID 21486440, 2011). "Because we reported that macrophages and IL-1β inactivate GSK3β in tumor cells, we next examined whether macrophages/IL-1β stabilize Snail through inhibition of GSK3β." (PMID 20661477, 2010). "Another question is whether other parameters such as inflammatory cytokines (e.g. IL-1β, IL-6, IL-8), placental growth factor or circulating tumour cells should have been explored to gain better insight in pharmacodynamic alterations at the tumoural level." (PMID 20823884, 2010). "However, we demonstrated that macrophages, TNFα and IL-1β increased the levels of Snail in tumor cells, a known Wnt target gene and regulator of tumor cell apoptosis." (PMID 20661477, 2010). "Whether IL-1β is produced by stromal cells or tumor cells themselves cannot be concluded, however the analysis of this database revealed that higher levels of IL-1β in tumors correlate with resistance to cetuximab." (PMID 20661477, 2010).